DUX4L8 (double homeobox 4 like 8 (pseudogene))
Synonyms: DUX2
Gene: Unprocessed pseudogene on chromosome 4 (190,067,935 to 190,069,209, forward strand). Ensembl gene ENSG00000281720.
Diseases named in the same sentence as DUX4L8 in open-access papers:
DUX4L8 is named in the same sentence as 3 diseases in open-access papers, as found by Europe PMC text mining. Sharing a sentence is not in itself a finding about the gene and the disease.
DUX4L8 shares sentences with these, for which no sentence is quoted: astrocytoma grade II (1 paper); colon carcinoma (1); ovary (1).